UGT8 (UDP glycosyltransferase 8)
Diseases named in the same sentence as UGT8 in open-access papers (continued):
Sharing a sentence is not in itself a finding about the gene and the disease.
non-small cell lung carcinoma (1 paper, 2021). A group of at least three distinct histological types of lung cancer, including non-small cell squamous cell carcinoma, adenocarcinoma, and large cell carcinoma. "However, inhibiting UGT8 alone could not inhibit cell proliferation and invasion of non-small cell lung carcinoma." (PMID 33324981, 2021).
triple-negative breast carcinoma (1 paper, 2023). An invasive breast carcinoma which is negative for expression of estrogen receptor (ER), progesterone receptor (PR), and human epidermal growth factor receptor 2 (HER2). "High UGT8 expression has been observed in triple-negative breast cancer to promote greater tumor progression." (PMID 38090559, 2023).
uveal melanoma (1 paper, 2021). A melanoma derived from melanocytes of the uveal tract. "We showed a significant association of high UGT8 expression with poor OS rates in Uveal Melanoma (UVM)." (PMID 34503303, 2021).
viral infection (1 paper, 2023). "GlcCer supplement in SPT-KO or UGCG-KO cells robustly facilitated viral infection to the similar levels of viral infection in control or UGT8-KO cells." (PMID 36920967, 2023).
tumor (18 papers, 2010 to 2026). "High expression of UGT8 in lung cancer tissues can maintain the malignancy of these tissues and is closely associated with drug resistance and tumor metastasis in patients, leading to poor patient prognosis." (PMID 36741721, 2022). "However, there is existing literature evidence elucidating their potential role in tumor biology, i.e, UGT8 is one such target encoding a protein belonging to the UDP-galactose:ceramide galactosyltransferase family." (PMID 39186767, 2024). "Similarly, genetic manipulation of UGT8 in vivo by downregulating this particular gene resulted in a higher level of ceramide generation, which caused significant tumour damage and diminishment of blood flow and oxygen saturation upon exposure to USMB and XRT." (PMID 35743121, 2022). "It has been discovered that UGT8 is linked with tumor progression and that elevated UGT8 levels may be crucial for the emergence of lung metastases." (PMID 36741721, 2022). "UGT8 synthesizes galactosylceramide (GalCer), an anti-apoptotic molecule that promotes BC cell survival within the tumor microenvironment and enhances resistance to anticancer drugs." (PMID 41781553, 2026). "Downregulated UGT8 had a higher degree of harm inflicted on the tumor cells compared to the control cells." (PMID 38967145, 2024). "The authors suggested that the defense mechanism of tumor cells can involve the activity of ceramide galactosyltransferase (UGT8), an enzyme that catalyzes the transfer of galactose to ceramide to generate galactosylceramide (GalCer)." (PMID 36613836, 2022). "For up-regulation of UGT8 in an in vitro model, PC3 cells were stably transfected with the coding sequence of UGT8, and for the in vivo work, xenograft tumours were generated by injecting the stably transfected PC3 cells in the hind leg of male mice." (PMID 35743121, 2022). "The study further evaluated tumour response in vivo using PC3 tumours xenograft in which UGT8 was up and down-regulated (this is explained in detail in the section below)." (PMID 35743121, 2022). "High UGT8 expression is closely related to the tumor grade and size in patients with basal breast cancer, and plays an important role in poor patient prognosis." (PMID 36741721, 2022). "This profile of genes includes AGPAT3, AKR1B1, PLD1, and UGT8, all of which have previously been reported to be involved in tumor proliferation." (PMID 34568042, 2021). "Recently, we reported that increased expression of urine diphosphate–galactose ceramide galactosyltransferase (UGT8) in BLBC facilitates tumor aggressiveness through the sulfatide-αVβ5 axis and predicts poor prognosis." (PMID 32296576, 2020). "Here experiments focused only on modifying the tumour cells making them up- or down-regulated in UGT8 which can affect lipid-based cell membrane repair." (PMID 28746357, 2017). "In UGT8 down-regulated tumours there was more overall fibrosis evident in Masson stained samples (increased blue staining)." (PMID 28746357, 2017). "Experiments were carried out with cells in vitro and tumours in vivo in which UGT8 levels had been up regulated or down regulated." (PMID 28746357, 2017). "Histology demonstrated more cellular damage in tumours with down-regulated UGT8 in comparison with control tumours." (PMID 28746357, 2017). "The results indicate an important role for UGT8 in affected responses of tumour cells to ultrasound stimulated microbubble radiation enhancement treatments." (PMID 28746357, 2017). "Ceramide immunolabelling was carried out on the control/sham, UGT8 up-regulated and UGT8 down-regulated tumours." (PMID 28746357, 2017). "These evidence including vascular disruption, tumour cell death and fibrosis give more insight into the mechanism of UGT8 action, where its down regulation indicated a role in the apoptotic process through its effect on ceramide metabolism." (PMID 28746357, 2017).
tumor (continued). "On the contrary tumours generated with UGT8 up-regulated PC3 illustrated less cell death overall, potentially because of ceramide depletion by the elevated UGT8 levels." (PMID 28746357, 2017). "Further evaluation of apoptotic cell death was carried out using TUNEL assay in control, UGT8 up-regulated, and UGT8 down-regulated tumours." (PMID 28746357, 2017). "Tumours where UGT8 was down-regulated illustrated various types of cell death that included apoptosis, necrosis, as well as fibrosis." (PMID 28746357, 2017). "The UGT8 up-regulated tumours exhibited a decreased level of ceramide production relative to the control tumours." (PMID 28746357, 2017). "In the UGT8 down-regulated tumours there was an overall increased level of ceramide compared to the control tumours." (PMID 28746357, 2017). "In this study UGT8 gene expression was modulated to test the importance of ceramide signalling in transducing the effects of blood vessels disruption into tumour cells." (PMID 28746357, 2017). "In the UGT8 down-regulated tumours greater levels of hypoxia were observed whereas in the UGT8 up-regulated tumours lesser levels of hypoxia were observed." (PMID 28746357, 2017). "Altogether, the significant differences in the expression of CerS2, CerS6, DEGS2, SMPD1, and UGT8 sphingolipid genes in tumor tissue go hand in hand with elevation of ceramide levels." (PMID 26528430, 2015). "Ceramide galactosyltransferase (UGT8) showed lower expression in tumor tissue, but there is yet little information regarding its impact on cancer development." (PMID 26528430, 2015). "The role of UGT8 and GalCer in tumor growth and formation of experimental metastases by control MDA-MB-231 cells and MDA/LUC-shUGT8 cells was studied in vivo in athymic nu/nu mice." (PMID 24391908, 2013). "All primary tumours except one stained more weakly with anti-UGT8 antibodies than did the lung metastases." (PMID 20648017, 2010). "It was found that the amounts of UGT8 protein and mRNA increased with tumour malignancy grades, and highly significant differences in UGT8 expression were found in G3 tumours vs G2 tumours." (PMID 20648017, 2010). "Comparison of the average values of the reaction intensities (IRS scale) showed a significant difference (Wilcoxon t-test, P<0.017) in UGT8 expression between primary and metastatic tumours." (PMID 20648017, 2010). "Using IHC, UGT8 expression was also studied in the primary tumours according to their malignancy grades." (PMID 20648017, 2010). "It was found that the expression of UGT8 in the tumour cells increased with increasing malignancy grade, reaching the highest values in the weakly differentiated cells (G3)." (PMID 20648017, 2010). "Significantly stronger staining with rabbit polyclonal antibodies directed against UGT8 was observed in the specimens from lung metastases than in paired primary tumours, confirming earlier results obtained at the mRNA level." (PMID 20648017, 2010). "For staining with anti-UGT8 antibodies, additional paraffin sections from 8 tumours of grade G1, seven tumours of grade G2, and 15 tumours of grade G3 were included." (PMID 20648017, 2010). "Conversely, tumor cells with upregulated UGT8 exhibited a lower mortality rate than control cells." (PMID 38967145, 2024). "Similarly, a significant increase in ceramide staining was observed in the down-regulated model compared to control or UGT8 up-regulated tumours." (PMID 35743121, 2022). "UGT8 overexpression is reported to be directly correlated with the malignancy grade of tumor cells." (PMID 36613836, 2022). "Further, when comparing cell death between the groups, specifically for the combined treatments, cell death was significantly higher in the UGT8 down-regulated tumours when compared to either that of the control/sham (P < 0.018), or to the UGT8 up-regulated (P < 0.018) tumours." (PMID 28746357, 2017). "In contrast, tumours with up-regulated UGT8 had less damage than control tumours." (PMID 28746357, 2017).
tumor (continued). "However, here the alteration of UGT8 activity in the tumour cells leading to changes in the amount of cell death indicates a broader role for ceramide in this mechanism." (PMID 28746357, 2017). "However, one candidate molecule is UGT8, which mediates the response of tumour cells to stress and is also involved in cell membrane repair." (PMID 28746357, 2017). "Tumor status induced a significant increase in the expression of CerS2 (p < 0.0001), CerS6 (p < 0.0001), DEGS2 (p < 0.0001), SMPD1 (p < 0.05), and CLN3 (p < 0.0001); and a significant decrease in the expression of UGT8 (p < 0.0001) compared with expression in the corresponding non-tumor tissue." (PMID 26528430, 2015). "When the average values of the reaction intensities (IRS scale) for tumours of different histological differentiation were compared by the Mann–Whitney U-test significant differences in UGT8 expression between malignancy grades G3 and G2 (P<0.01) as well as G3 and G1 (P<0.001) were found." (PMID 20648017, 2010). "In contrast, DPEP1, HADH, PLIN2, SCD5, SLC44A4, and UGT8 may function to suppress tumor growth via the regulation of immune cells with antitumor activity such as resting memory CD4 T cells, resting NK cells, M2 macrophages, resting and activated DCs, and resting mast cells." (PMID 38090559, 2023). "UGT8 and GAL3ST1 showed higher expression levels in tumor tissue compared to normal tissue, with significance reached for GAL3ST1." (PMID 39000386, 2024). "UGT8 and GAL3ST1 showed higher mRNA levels in iCCA tumor tissue as well as in CCA cell lines from different anatomical regions of the biliary tract compared to normal tissue/cells." (PMID 39000386, 2024). "In order to investigate the effect of UGT8 up- and down-regulation on tumour tissues, xenograft tumours were generated using stably transfected PC3 cells up- and down-regulated with respect to UGT8 expression." (PMID 28746357, 2017). "In a small cohort of patients from the Maastricht University Medical Center and Uniklinik RWTH Aachen, UGT8 and GAL3ST1 expression was measured by quantitative real-time PCR (qRT-PCR) in 6 tumor tissue and 10 tumor-distal liver specimens from patients with intrahepatic CCA." (PMID 39000386, 2024). "The up-regulation of UGT8 exhibited lower intracellular ceramide levels with no significant tumour vasculature damage." (PMID 35743121, 2022). "Mechanistically, UGT8 is transcriptionally upregulated by Sox10 to induce the biosynthesis of sulfatide, which then activates integrin αVβ5-mediated signaling, including TGF-β and NF-κB, to potentiate tumor viability and metastasis." (PMID 32296576, 2020). "Interestingly, highly increased expression of UGT8 was also observed in primary node-positive tumours as compared with that in node-negative primary tumours." (PMID 20648017, 2010).
cancer (12 papers, 2010 to 2025). A tumor composed of atypical neoplastic, often pleomorphic cells that invade other tissues. "Overall, our results showed that the expression levels of 6 UGT genes (1A1, 1A6, 1A7, 2A3, 2B15, UGT8) were significantly associated with OS rates in at least one cancer type." (PMID 34503303, 2021). "UGTs genes are upregulated in tissues associated with drug metabolism, such as cancers of the liver, kidney, intestine, and pancreas, such as UGT1A6, UGT1A9, UGT1A10, UGT2A3, UGT2B7, and UGT8, and they are significantly associated with increased overall survival in cancer." (PMID 36741721, 2022). "In other work, a gene responsible formembrane biogenesis and repair involved in the transfer of galactose to ceramide,UDP glycosyltransferase 8 (UGT8) was experimentally upregulated or downregulated inprostate cancer xenografts." (PMID 36412102, 2022). "Of the 20 UGT genes assessed, 6 (1A6, 1A9, 1A10, 2A3, 2B7, UGT8) showed high expression in at least 5 different cancer types." (PMID 34503303, 2021). "In general, the balance between Cer and HexCers as well as the rate-limiting enzymes in Cer glycosylation such as UGCG and UGT8, are actively contributing to many aspects of cancer signaling, proliferation, and resistance." (PMID 34637456, 2021). "Among these genes, 8 were upregulated (1A3, 1A6, 1A7, UGT8) or downregulated (1A8, 2A3, 3A2, 2B7) consistently in at least 2 cancer types, and 5 genes (1A1, 1A9, 1A10, 2A1, 2B15) showed upregulation in some cancers but downregulation in other cancer types." (PMID 34503303, 2021). "UGT8 is an enzyme, which is involved in ceramide metabolism and its levels were found to be elevated in a number of cancers." (PMID 28746357, 2017). "Targeted vascular-disrupting therapy combined with targeting localized UGT8 make the approach a good candidate for further exploration and optimization to achieve an effective cancer therapy with minimal adverse effects on healthy tissues." (PMID 28746357, 2017). "Expression of UGT8 in the paraffin sections of the cancer tissue specimens was analysed using rabbit polyclonal antibodies." (PMID 20648017, 2010). "Therefore, we propose that the inhibition of UGT8 by knockout of the UGT8 gene or using chemical inhibitors of the UGT8 enzyme would increase cancer cell sensitivity to conventional chemotherapy." (PMID 38254878, 2024). "Kaplan–Meier plots and logrank tests revealed that six UGT genes were significantly associated with increased overall survival (OS) rates [UGT1A1 (LUSC), UGT1A6 (ACC), UGT1A7 (ACC), UGT2A3 (KIRC), UGT2B15 (BLCA, SKCM)] or decreased OS rates [UGT2B15 (LGG), UGT8 (UVM)] in specific cancers." (PMID 34503303, 2021). "Notably, cancers derived from drug metabolizing tissues (liver, kidney, gut, pancreas) expressed the largest number of UGT genes (COAD, KIRC, KIRP, LIHC, PAAD); six UGT genes (1A6, 1A9, 1A10, 2A3, 2B7, UGT8) showed high expression in five or more different cancers." (PMID 34503303, 2021). "However, information about GalCer and UGT8 in cancer cells is scarce." (PMID 24391908, 2013). "The expression body map, normalized to transcripts per million (TPM) revealed the median expression of UGT8 and GAL3ST1 in different human cancers." (PMID 39000386, 2024). "The high expression of UGT1A8, UGT8, UGT1A7, UGT2A3, and UGT2B15 in these cancers and its relation to good patient prognosis is very interesting and deserves further investigation." (PMID 36741721, 2022). "Notably, UGT8 and UGT1A6 showed high expression in 18 and 13 different cancer types, respectively." (PMID 34503303, 2021). "Finally, differential expression analysis of 611 patients from 12 TCGA cancers identified 16 UGT genes (1A1, 1A3, 1A6, 1A7, 1A8, 1A9, 1A10, 2A1, 2A3, 2B4, 2B7, 2B11, 2B15, 3A1, 3A2, UGT8) that were up/downregulated in at least one cancer relative to normal tissues." (PMID 34503303, 2021).
infection (3 papers, 2013 to 2024). The state of being infected such as from the introduction of a foreign agent such as serum, vaccine, antigenic substance or organism. "Since GW2580 treatment during infection partially reversed the effects of infection on Ugt8a expression levels, we questioned whether secreted factors from activated microglia were capable of directly suppressing Ugt8 expression in primary OL cultures." (PMID 37596606, 2023). "In contrast, the level of mRNAs encoding the synthases responsible for the conversion of GlcCer to LacCer increased only slightly during the infection period, and not at all for UGT8, the enzyme that converts Cer to GalCer." (PMID 38300320, 2024).
adenocarcinoma (1 paper, 2025). A common cancer characterized by the presence of malignant glandular cells. "Although it has not been proven whether the compound directly binds to UGT8 to inhibit its enzymatic activity, compound 19 has been shown to decrease the amount of GalCer in the adenocarcinoma cell line OE19 and the mouse brain and kidney." (PMID 39658193, 2025).
UGT8 also shares sentences with these, for which no sentence is quoted: ovarian carcinoma (2 papers); Ataxia (1); bladder cancer (1); breast tumours (1); colon cancer (1); demyelinating disease (1); esophageal cancer (1); gastric cancer (1); glioma of the brain (1); Huntington disease (1); hyperlipidemia (1); Krabbe disease (1); lysosomal storage disorders (1); metachromatic leukodystrophy (1); metastatic disease (1); mood disorder (1); Obesity (1); osteoporosis (1); pancreatic cancer (1); Paralysis (1); temporal lobe epilepsy (1).